SLC36A2 (solute carrier family 36 member 2)
Description:
Electrogenic proton/amino acid symporter with a high selectivity for the small side chains amino acids glycine, alanine and proline, where both L- and D-enantiomers are transported. Extension of the backbone length, as in beta-alanine and 4-aminobutanoate or methylation of the amino group, as in sarcosine and N,N-dimethylglycine, are also tolerated but decrease transport efficiency. A free carboxyl group is preferred.
Synonyms: PAT2; TRAMD1; tramdorin
Tractability: Antibody: UniProt places it where antibodies can reach, with high confidence; its Gene Ontology location is reachable by antibodies, with high confidence; UniProt predicts a signal peptide or a membrane-spanning region.
Gene: Protein-coding gene on chromosome 5 (151,314,972 to 151,347,590, reverse strand). Ensembl gene ENSG00000186335.
Subcellular location: Cell membrane; Endoplasmic reticulum membrane; Recycling endosome membrane
Pathways (Reactome):
Transport of small molecules: Amino acid transport across the plasma membrane; Proton-coupled neutral amino acid transporters
Disease: Defective SLC36A2 causes iminoglycinuria (IG) and hyperglycinuria (HG)
Gene Ontology:
Molecular function: amino acid:proton symporter activity; proline:proton symporter activity; amino acid transmembrane transporter activity; gamma-aminobutyric acid:proton symporter activity; glycine transmembrane transporter activity; L-alanine transmembrane transporter activity; L-proline transmembrane transporter activity
Biological process: proline transmembrane transport; amino acid transport; glycine transport; L-alanine transport; proton transmembrane transport; gamma-aminobutyric acid transport
Cellular component: extracellular exosome; plasma membrane; endoplasmic reticulum membrane; recycling endosome membrane
Genetic constraint (gnomAD): Loss-of-function variants: 36 observed, 43.33 expected, observed/expected ratio (o/e) 0.83, 90% interval 0.64 to 1.1. The upper end of that interval is the gene's LOEUF score, 1.1, which puts it in group 4 of 6, group 1 being the genes least tolerant of losing a copy. Missense variants: 585 observed, 634.14 expected, observed/expected ratio (o/e) 0.92, 90% interval 0.86 to 0.99. Synonymous variants: 234 observed, 249.19 expected, observed/expected ratio (o/e) 0.94, 90% interval 0.84 to 1.05.
Gene-disease validity (ClinGen):
ClinGen rates the evidence that SLC36A2 causes each of these diseases.
iminoglycinuria (autosomal recessive): Limited. A metabolic disorder resulting from defective renal tube reabsorption of proline, hydroxyproline and glycine.
Homologues: Orthologues: chimpanzee SLC36A2 (99% identical), macaque SLC36A2 (94% identical), dog SLC36A2 (85% identical), rabbit SLC36A2 (84% identical), mouse Slc36a2 (82% identical), rat Slc36a2 (82% identical), pig SLC36A2 (81% identical), guinea pig SLC36A2 (80% identical), Drosophila melanogaster CG13384 (39% identical), Drosophila melanogaster CG7888 (33% identical), Drosophila melanogaster CG16700 (32% identical), Caenorhabditis elegans slc-36.1 (30% identical), and 14 more. Paralogues in human: SLC36A1 (70% identical), SLC36A3 (55% identical), SLC36A4 (50% identical), SLC38A4 (20% identical), SLC38A3 (20% identical), SLC38A2 (20% identical), SLC38A1 (20% identical), SLC38A6 (19% identical), SLC38A5 (18% identical), SLC38A10 (18% identical), SLC32A1 (17% identical), SLC38A7 (17% identical), and 3 more.
Diseases named in the same sentence as SLC36A2 in open-access papers:
SLC36A2 is named in the same sentence as 18 diseases in open-access papers, as found by Europe PMC text mining. Sharing a sentence is not in itself a finding about the gene and the disease. The quoted sentences say what the papers report.
iminoglycinuria (4 papers, 2011 to 2025). "Mutations in genes (SLC36A2, SLC6A20, and SLC6A18) encoding amino acid transporters are responsible for iminoglycinuria." (PMID 41142409, 2025). "The SLC36A2 (PAT2) gene was identified as the major gene responsible for iminoglycinuria, a renal defect characterised by reduced reabsorption of glycine, proline and hydroxyproline (Online Mendelian Inheritance in Man, OMIM: 242600)." (PMID 20691150, 2011).
Hyperglycinuria (3 papers, 2011 to 2019). An increased concentration of glycine in the urine. "A physiological role played by PAT2 in amino acid reabsorption in the renal proximal tubule is demonstrated by mutations in SLC36A2 that lead to an iminoglycinuric phenotype (imino acid and glycine uria) in humans." (PMID 20691150, 2011).
Obesity (2 papers, 2017 to 2019). Accumulation of substantial excess body fat. "Similar to obesity, diabetes was associated with an increase in Lep expression in eAT (P ≤ 0.05), but a downregulation of Slc36a2 expression in mAT (P ≤ 0.05)." (PMID 29138472, 2017).
Aminoaciduria (1 paper, 2025). An increased concentration of an amino acid in the urine. "The review highlighted 9 genes associated with aminoacidurias, including SLC3A1 (rBAT), SLC7A9 (bo,+AT), SLC6A19 (BoAT1), SLC7A7 (y+LAT1), SLC7A6 (y+LAT2), SLC36A2 (PAT-2), SLC6A20 (SIT-1), SLC6A18 (BoAT3), and SLC1A1 (EAAT3)." (PMID 41142409, 2025).
coronary artery disease (1 paper, 2022). "Among these, expression of SLC36A2 in epicardial adipose tissue is linked with an increased risk of coronary artery disease." (PMID 36078037, 2022).
cancer (1 paper, 2021). A tumor composed of atypical neoplastic, often pleomorphic cells that invade other tissues. "Of these genes, six lncRNA (AL360091.3, AL360175.1, AC025254.1, AC093801.1, AC092354.1 and AC016722.1); four pseudogenes (RBM22P2, AC073324.1, OR1X1P, RPL7P52 and MTND5P25) and coding SLC36A2 and SDS and have not previously been shown to be transcripts in cancer." (PMID 34026616, 2021).
SLC36A2 also shares sentences with these, for which no sentence is quoted: infection (3 papers); tumor (3); bronchopulmonary dysplasia (1); chronic lung disease (1); diabetes (1); glaucoma (1); lung carcinoma (1); lymphoma (1); metastatic tumors (1); Retinal dystrophy (1); retinopathy (1); Tay-Sachs disease (1).